CACNA1A (calcium voltage-gated channel subunit alpha1 A)
Diseases named in the same sentence as CACNA1A in open-access papers (continued):
Sharing a sentence is not in itself a finding about the gene and the disease.
coloboma (1 paper, 2009). An abnormality in which a part of a structure in one or both eyes is missing. "The lethargic, tottering, stargazer, Coloboma, and Cacna1a-/- mutant mouse models of absence epilepsy each exhibit significant increases in thalamic T-type calcium currents despite the absence of evidence for enhanced T-type channel subunit expression." (PMID 19480703, 2009).
Down syndrome (1 paper, 2022). "Therefore, CACNA1A-associated disorders and neurodevelopmental disorders, including Down syndrome, may share a common mechanism of compromised maturation of the hippocampus." (PMID 35548926, 2022).
Duchenne muscular dystrophy (1 paper, 2025). Duchenne muscular dystrophy (DMD) is a neuromuscular disease characterized by rapidly progressive muscle weakness and wasting due to degeneration of skeletal, smooth and cardiac muscle. "This approach has shown success in treating conditions such as Duchenne muscular dystrophy and spinal muscular atrophy, indicating its potential for CACNA1A-related disorders." (PMID 40111503, 2025).
endometriosis (1 paper, 2012). The growth of functional endometrial tissue in anatomic sites outside the uterine body. "When we compared those genes with methylated promoters in samples of OCCA with and without endometriosis, only CACNA1A had a significantly higher promoter methylation status in OCCA samples without endometriosis (47.2%, 17/36) compared to those associated with endometriosis (0%, 0/8) (p = 0.013)." (PMID 22871047, 2012). "And the methylation of CACNA1A gene only participates in the carcinogenesis of OCCA without endometriosis." (PMID 22871047, 2012). "Methylation of CACNA1A is involved in the carcinogenesis of OCCA without endometriosis." (PMID 22871047, 2012).
episodic ataxia type 5 (1 paper, 2022). Episodic ataxia type 5 (EA5) is an extremely rare form of Hereditary episodic ataxia characterized by recurrent episodes of vertigo and ataxia lasting several hours. "Brugada Syndrome type 4 and Episodic ataxia type 5 present causative mutations in genes coding for CaVβs proteins and other CaV subunits (CACNA2D1 and CACNA1A, and CACNA1A respectively–MalaCard database), corroborating CaVβ involvement in pathological mechanisms in a CaV-linked way." (PMID 35465309, 2022).
focal dystonia (1 paper, 2021). A dystonia that is localized to a specific part of the body. "Furthermore, loss-of-function mutations of CACNA1A have been clearly linked to benign paroxysmal torticollis of infancy as well as to focal dystonia." (PMID 33435586, 2021).
gastric cancer (1 paper, 2015). A primary or metastatic malignant neoplasm involving the stomach. "In contrast, an opposite trend was observed in breast and stage IV gastric cancer with low expression of CACNA1A." (PMID 26147197, 2015). "In other words, CACNA1A was down-regulated in breast and gastric cancer." (PMID 26147197, 2015).
glioblastoma (1 paper, 2024). The most malignant astrocytic tumor (WHO grade IV). "In primary glioblastoma, CACNA1A expression is upregulated and involved in the development of cancer stem cells (CSC) and the regulation of related signaling pathways." (PMID 38877096, 2024).
infarction (1 paper, 2023). A localised pathological necrosis of tissue resulting from obstruction of the blood supply usually by a thrombus, an embolus, or vascular torsion. "After infarction, the expression of CACNA1A can enhance cardiac differentiation of brown adipose-derived stem cells to regenerate the myocardium after infarction." (PMID 37474895, 2023).
Leukoencephalopathy (1 paper, 2020). This term describes abnormality of the white matter of the cerebrum resulting from damage to the myelin sheaths of nerve cells. "Other genetic mutations known to be associated with similar clinically presenting diseases (FHM1 in CACNA1A, FHM2 in ATP1A2, and mutations within COL4A1 cause COL4A1-associated leukoencephalopathy) have been identified through follow-up testing requested by clinicians." (PMID 31915071, 2020).
metastatic disease (1 paper, 2019). "The observed overexpression of CACNA1A, CACNA1C, and CACNA1D suggests that they are likely targets for cancer treatment, as blockage or partial inhibition of their expression could help to modulate the progression of metastatic disease." (PMID 31416476, 2019).
neuroblastoma (1 paper, 2021). Neuroblastoma (NB) is the most common solid, extracranial childhood tumor. "Functional analysis in the cell line model (SH-SY5Y neuroblastoma cell line) revealed that CAG repeats of pathogenic expansion in the C-terminus of the CACNA1A gene probably lead to activation of apoptosis factors (Bcl-2/Bax, caspase, and PARP) and induce cell apoptosis in nerve cells." (PMID 34727962, 2021).
oropharyngeal cancer (1 paper, 2021). Carcinoma, predominantly squamous cell, arising from the epithelial cells of the oropharynx. "Additionally, with epigenetic exploration, it was shown that methylation of CACNA1A is one of the markers for irradiation efficacy in oropharyngeal cancer." (PMID 34440356, 2021).
ovarian clear cell adenocarcinoma (1 paper, 2021). A malignant glandular epithelial neoplasm characterized by the presence of clear and hobnail cells. "Furthermore, CACNA1A has also been shown to have a high promoter methylation status in ovarian clear cell adenocarcinoma." (PMID 34440356, 2021).
parkinsonian disorder (1 paper, 2025). A group of disorders which feature impaired motor control characterized by bradykinesia, MUSCLE RIGIDITY; TREMOR; and postural instability. "Other repeat expansion genes, including ATXN3, CACNA1A, and PRNP, typically associated with parkinsonian disorders, do not exhibit an association with PD in our cohort." (PMID 41009775, 2025).
pelvic organ prolapse (1 paper, 2024). Abnormal descent of a pelvic organ resulting in the protrusion of the organ beyond its normal anatomical confines. "Homozygosity for Agpat1 or Cacna1a mutations led to early lethality; homozygosity for Loxl1 mutations led to pelvic organ prolapse, preventing aging." (PMID 38770563, 2024).
periodic paralysis (1 paper, 2022). "We now routinely screen patients with strong clinical evidence of periodic paralysis and negative PP genetics for CACNA1A mutations." (PMID 34817893, 2022).
Sepsis (1 paper, 2019). Sepsis is defined as life-threatening organ dysfunction caused by a dysregulated host response to infection. "Previous research has described an increased expression of synaptic genes during the progression from normal aging to neurodegenerative disease, including genes we observed to increase in older males on day 4 of sepsis (Cacnb1, Cacna1a, Ephb4, Glul, Jph3, Mink1, Nrxn2, Grasp)." (PMID 31278440, 2019).
syringomyelia (1 paper, 2022). Syringomyelia is characterized by cerebrospinal fluid (CSF)-filled cavities (syrinx) inside the spinal cord, either as a result of a known cause (secondary syringomyelia, SS) or, more rarely, due to an unknown cause (primary syringomyelia, PS). "Three out seven patients had a co-occurring CACNA1A deletion, one subject had a microdeletion not involving CACNA1A but was affected with CM1 and syringomyelia and one subject (Pt 1) carrying a pathogenetic NFIX variant had CM1 with syringomyelia." (PMID 35717370, 2022).
testis cancer (1 paper, 2015). "CACNA1F only showed high expression in testis cancer, whereas CACNA1A, CACNA1C, and CACNA1D were highly expressed in most types of cancer." (PMID 26147197, 2015).
trigeminal neuralgia (1 paper, 2021). Trigeminal neuralgia is a nerve disorder that causes a stabbing or electric-shock-like pain in parts of the face. "A novel missense mutation in the CACNA1A gene that encodes the pore forming α1 subunit of the CaV2.1 voltage-gated calcium channel was identified in a patient with trigeminal neuralgia." (PMID 33413531, 2021).
triple-negative breast carcinoma (1 paper, 2021). An invasive breast carcinoma which is negative for expression of estrogen receptor (ER), progesterone receptor (PR), and human epidermal growth factor receptor 2 (HER2). "Methylation of CACNA1A is also associated with triple-negative breast cancer." (PMID 34440356, 2021).
neurological disorders (48 papers, 2008 to 2026). "Additional findings included a heterozygous missense variant in CACNA1A (p.Arg1678Cys), a gene linked to neurological disorders with broad phenotypic variability." (PMID 41594250, 2026). "The relevance of CaV2.1 in shaping brain development and function is demonstrated by the wide spectrum of episodic and progressive neurological disorders caused by mutations in the CACNA1A gene." (PMID 40514452, 2025). "The broad spectrum of CACNA1A-related neurological disorders relies on the large number of different disease-causing variants." (PMID 40514452, 2025). "Gaining a comprehensive understanding of the CACNA1A gene and its role in neurological disorders is crucial for unraveling underlying mechanisms." (PMID 40111503, 2025). "CACNA1A gene variants have been associated with a diverse array of neurological disorders, highlighting the critical role of this gene in normal neuronal function." (PMID 40111503, 2025). "Mutations in CACNA1A, the gene encoding the principal CaV2.1 α1A subunit, cause a broad spectrum of neurological disorders." (PMID 35655070, 2022). "Any pathogenic alterations in the CACNA1A gene, which lead to changed calcium influx, are associated with neurological disorders." (PMID 34727962, 2021). "Each of the neurological disorders is associated with a different CACNA1A mutation, suggesting differential effects on Ca2+ signaling." (PMID 32765211, 2020). "In this study, we explored the molecular and functional properties of iPSC-derived neural models to investigate the role of CACNA1A in human neurogenesis and to uncover the cellular development mechanisms underpinning neurological disorders caused by CACNA1A deficiency." (PMID 40514452, 2025). "Splicing variants can also affect channel function under pathological conditions although their phenotypic implication concerning inherited neurological disorders linked to CACNA1A mutations remains unknown." (PMID 39568055, 2024). "CACNA1A has previously been associated with a wide spectrum of neurological disorders." (PMID 34440356, 2021). "In conclusion, CACNA1A mutations can lead to a wide spectrum of neurological disorders." (PMID 33425808, 2020). "The iPSC-derived neuronal models developed in this study will pave the way for future therapeutic testing for neurological disorders involving CACNA1A." (PMID 40514452, 2025). "We aimed to contribute to the existing literature with this study, broadening knowledge about CACNA1A and its implications in neurological disorders." (PMID 40111503, 2025). "CACNA1A-related Hemiplegic Migraine (HM) is a rare neurological disorder distinguished by paroxysmal episodes of hemiparesis/hemiplegia with and without headache." (PMID 39555480, 2024). "Mutations in the CACNA1A gene encoding the pore-forming subunit of the CaV2.1 channel cause several neurological disorders, in particular FMH1, SCA6 and EA2 (Pietrobon, 2010, Jen, 2008)." (PMID 27260834, 2016). "As an example, the CACNA1A gene, important for calcium channel function and neural communication, is associated with a broad spectrum of neurological disorders, but has not yet been linked to SZ or neural oscillations." (PMID 40806641, 2025). "In this regard, the iPSC-derived models developed in this study may provide the foundation for future testing of potential therapeutic approaches for CACNA1A-related neurological disorders." (PMID 40514452, 2025). "CACNA1A uncovered in TMSC transcriptome (involved in dopaminergic, GABAergic, serotonergic and glutamatergic synapse) is responsible for communication between neurons by ion exchange and mutations in this gene results into neurological disorder." (PMID 33506763, 2021). "Furthermore, CACNA1A gene function can be altered either by de novo SNVs or trinucleotide repeat expansion (CAG) to manifest with a broad range of neurological disorders." (PMID 28327206, 2017).
neurological disorders (continued). "It is possible that the trafficking or signal modulation of CACNA1A differs between humans and other mammals as a result of adaptation of the central nervous system, which could result in humans being more prone to these neurological disorders." (PMID 18837980, 2008). "We report the clinical features of 41 patients with non-polyglutamine CACNA1A disease from a national reference center for rare neurological diseases in Austria." (PMID 39110218, 2024). "Hypermethylated genes involved in neurological disorders include AGAP1, CACNA1A, and OTX2." (PMID 32850550, 2020).
cancer (18 papers, 2015 to 2025). A tumor composed of atypical neoplastic, often pleomorphic cells that invade other tissues. "Methylation of the CACNA1A gene is apparently associated with several cancers." (PMID 27342111, 2016). "We also found that 7 out of 21 cancer tissues showed high expression of CACNA1A, and it was categorized in the top 10% of the most increased genes." (PMID 26147197, 2015). "Pathways derived from NOTCH3, PARD3, CACNA1A, MAX, RAD50, FUS and LMO2 were cancer-related." (PMID 34540367, 2021). "The observation of overexpression of CACNA1A, CACNA1C, and CACNA1D could make them likely targets in cancer treatment, as it suggests that blockage or partial inhibition of their expression could help to modulate the status of metastatic diseases." (PMID 26147197, 2015). "Given the previous data on CACNA1A, in which ectopic expression of a microRNA is able to perturb IRES function, this is extremely important and represents a starting point for the development of this type of therapeutic for treatment-resistant HER2-amplified cancers." (PMID 36076950, 2022).
neurodevelopmental disorder (17 papers, 2015 to 2025). A behavioral and cognitive disorder with onset during the developmental period that involves impaired or aberrant development of intellectual, motor, or social functions. "Genetic summary of 6 patients with CACNA1A-associated neurodevelopmental disorders from our hospital." (PMID 37555011, 2023). "A recent comprehensive clinical and radiological study suggested that CACNA1A-associated phenotypes are neurodevelopmental disorders." (PMID 35548926, 2022). "Our observations support a causative role of gain-of-function CaV2.1 mutations in congenital ataxia, a neurodevelopmental disorder at the severe-most end of CACNA1A-associated phenotypic spectrum." (PMID 26716990, 2015). "CACNA1A variants are associated with severe neurodevelopmental disorders (NDDs), but the underlying mechanisms remain unclear." (PMID 41456028, 2025). "Among the gene families implicated in neurodevelopmental disorders, voltage-gated calcium channel genes—including CACNA1A (encoding Cav2.1), CACNA1C (Cav1.2), and CACNA1H (Cav3.2)—are of particular interest due to their central roles in neuronal signaling, excitability, and neurodevelopment." (PMID 40725423, 2025). "Thus, we aimed to investigate genotype–phenotype correlations, underlying mechanisms, and potential therapies for the for CACNA1A-related neurodevelopmental disorders." (PMID 37555011, 2023). "In the present study, we collected clinical and genetic data related to epileptic patients with CACNA1A pathogenic variants and investigated any meaningful relationship between age at onset, neurodevelopmental disorders, type of seizures, brain imaging abnormalities, genotype, and protein domains." (PMID 34727962, 2021). "Although DCM development is underway for CACNA1A-related neurodevelopmental disorders as a whole, individuals with a CACNA1A-related HM diagnosis will only represent a small percentage of the individuals in this cohort." (PMID 39555480, 2024). "The PubMed database was systematically searched for all reported patients with CACNA1A-related neurodevelopmental disorders until February 2023." (PMID 37555011, 2023). "Six children diagnosed with CACNA1A-related neurodevelopmental disorders at Xiangya Hospital, Central South University from April 2018 to July 2021 were enrolled." (PMID 37555011, 2023). "We aimed to summarize genotype–phenotype correlations and potential treatment for CACNA1A-related neurodevelopmental disorders." (PMID 37555011, 2023). "For example, it remains to be elucidated if CACNA1A-related neurodevelopmental disorders represent separate entities or rather an age-dependent stage within an evolving phenotype." (PMID 33737904, 2021). "However, little is still known about genotype–phenotype correlations in CACNA1A-related neurodevelopmental disorders and DEE." (PMID 39416668, 2024).
tumor (14 papers, 2010 to 2025). "Some alterations, such as CEBPA and CACNA1A mutations, were completely or predominantly late‐clonal and often occurred after genome duplication, suggesting that these alterations contribute to tumour maintenance and progression." (PMID 35061935, 2022). "HLTF, BNIP3, H2AFX, CACNA1G, TGIF, ID4 and CACNA1A were identified as novel tumor suppressor candidates methylated in lung tumors." (PMID 20849603, 2010). "VCGG channels, including CACNA1C, CACNA1D, CACNA1F, CACNA1E, CACNA1A, CACNA1G, CACNA1I, showed significantly higher expression in KIRC than normal cases, whereas CACNA1S and CACNA1H showed higher expression in normal than tumor cases." (PMID 36588677, 2022).
neurodegenerative disease (11 papers, 2015 to 2021). A disorder of the central nervous system characterized by gradual and progressive loss of neural tissue and neurologic function. "The CAG repeat in CACNA1A encodes a polyglutamine (polyQ) repeat, thus classifying SCA6 as one of the members of the polyQ family of neurodegenerative diseases." (PMID 27979829, 2016). "SCA6 is a late-onset neurodegenerative disease caused by a polyglutamine tract expansion at the C terminal of CACNA1A." (PMID 25811491, 2015).
movement disorder (8 papers, 2016 to 2025). Neurological conditions resulting in abnormal voluntary or involuntary movement, which may impact the speed, fluency, quality and ease of movement. "Myoclonus is the main type of movement disorder associated with CACNA1A (approximately 82.8%), KCNA2 (75%), SCN1A (approximately 61.5%), and SCN8A (60%) mutations." (PMID 40217411, 2025). "Cacna1a is involved in movement disorder and expression of Nfix can influence neural stem cell differentiation." (PMID 35402909, 2022).
psychiatric disorder (6 papers, 2016 to 2023). A disorder characterized by behavioral and/or psychological abnormalities, often accompanied by physical symptoms. "In humans loss-of-function mutations in the CACNA1A were implicated in neurological and psychiatric diseases." (PMID 31533613, 2019). "Furthermore, FMRP has direct interaction with CACNA1A, and so it can probably explain the cause of psychiatric disorder in the clinical spectrum related to this gene." (PMID 34727962, 2021). "Intriguingly, a genome-wide analysis has also revealed that CACNA1B along with the CACNA1A gene play a shared effect on 5 major psychiatric disorders, including MDD35." (PMID 28769055, 2017). "Polymorphisms in CACNA1A and CACNB2 were demonstrated to be trans-diagnostic markers of major psychiatric disorders." (PMID 27091189, 2016).
genetic disorders (4 papers, 2020 to 2024). "CACNA1A, the gene encoding CaV2.1, is associated with multiple genetic disorders;7,8 in contrast, there are very few identified human or animal pathological variants of CACNA1B, encoding CaV2.2, which underlies N-type CaV channels." (PMID 38020068, 2024). "Advances in genetic testing have broadened the KCNA1 and CACNA1A phenotypes, and detected EA as an unusual presentation of several other genetic disorders." (PMID 37008993, 2023).
cardiovascular disease (2 papers, 2022 to 2023). "The hsa_circ_0003935 expression was transcribed by CACNA1A, which has not been reported in cardiovascular diseases." (PMID 35845080, 2022).